HGF (hepatocyte growth factor)
Diseases named in the same sentence as HGF in open-access papers (continued):
Sharing a sentence is not in itself a finding about the gene and the disease.
tumor (continued). "Interestingly, the “newly opened” vessels (vessels that could not be detected before administration of HGF) caused by HGF treatment were mainly responsible for tumor blood volume increase." (PMID 28485003, 2017). "HGF/MET’s involvement with E2F-1 also implicates its binding with RB, a well-known tumor suppressor." (PMID 28696366, 2017). "The current study provides evidence for an interaction between fibroblasts and NSCLC cells via the HGF/Met signaling pathway, which affects NSCLC cell survival and tumor progression." (PMID 28619066, 2017). "Our BsAb can inhibit HGF-induced growth and migration of c-MET-addicted tumor cells, promote the apoptosis of tumor cells, and rescue IL-2 secretion of Jurkat T cells." (PMID 28404966, 2017). "For example, after stimulation by HGF, cMet triggers the internalization and subsequent degradation of E-cadherin in carcinoma cells, resulting in EMT and tumor cell dissemination." (PMID 29112161, 2017). "In vitro, our BsAb inhibited HGF-induced growth and migration of c-MET-addicted tumor cells, and promoted apoptosis in tumor cells, even more effectively than JNJ, a known c-MET inhibitor." (PMID 28404966, 2017). "HGF activates MET, expressed on tumor cells, and drives resistance to EGFR-targeted therapy by triggering ERK and PI3K/AKT pro-survival signaling and by promoting epithelial-mesenchymal transition." (PMID 28968967, 2017). "The interplay of tumor cells and their microenvironment is crucial in the growth of solid tumors and the VEGF/VEGFR and the HGF/cMET pathways are key mediators of such interaction." (PMID 29228696, 2017). "On the other hand, stroma-derived HGF protects CRC cells against glucose starvation-induced apoptosis, allowing them to survive longer in a poorly vascularized tumor." (PMID 28445144, 2017). "Our findings, demonstrating that reduced expression of MCT1 dramatically limits EGF- and HGF-induced cell motility, are somewhat expected given the known role of MCT1 transporter activity in tumor progression." (PMID 27127175, 2016). "Previous studies showed that in addition of factors like VEGFA and bFGF, which promote tumor angiogenesis, myelomonocytic cells also produce EGF, HGF, MMP-9 and other cytokines that directly enhance the tumor cell survival, growth and invasion." (PMID 27391260, 2016). "NKTCL cells were found to produce HGF and activate the HGF/c-MET signaling pathway for the tumor cell proliferation in an autocrine manner." (PMID 27923392, 2016). "Expression of hSulf-1 can also reduce HGF-mediated PI3K/AKT pathway activity, thereby inhibiting tumor growth and metastasis." (PMID 27806323, 2016). "HGF/SF and its receptor, the tyrosine kinase MET, play a central role in many aspects of tumor progression." (PMID 26623562, 2016). "This tumor-tropic behavior has been reported to be stimulated by chemokines released from hypoxic tumors via signaling pathways such as SDF-1/CXCR4 and HGF/c-Met." (PMID 27965712, 2016). "Tumor cell migration is mainly stimulated by various growth factors, such as insulin-like growth factor-1 (IGF-1), epithermal growth factor (EGF), hepatocyte growth factor (HGF), and basic fibroblast growth factor (bFGF)." (PMID 27363031, 2016). "In conclusion, our analysis suggests baseline circulating MET and HGF as prognostic factors in second-line HCC, and tumor MET as a prognostic and predictive biomarker of HCC and tivantinib activity." (PMID 27579536, 2016). "The tyrosine-kinase receptor c-Met (also known as MET) and its ligand, the hepatocyte growth factor (HGF), have been shown to be involved in tumour growth, invasion and metastasis in many human cancers of epithelial origin." (PMID 27896673, 2016). "Myofibroblasts are the predominant stromal cell type in most carcinomas and have been shown to take part in tumour proliferation by secreting a number of growth factors, including IGF-1, IGF-II and HGF." (PMID 26979829, 2016).
tumor (continued). "The transcription of the MMPs is induced by inflammatory cytokines, such as IL-1, IL-6, TNF-α, and growth factors such as EGF, HGF, and TGF-β, giving them a preponderant role in the chronic inflammation which is present in the tumour microenvironment." (PMID 26913068, 2016). "Accumulated evidence suggested that HGF plays the role of an EMT regulator and accelerates the tumor-promoting activity in various cancer progressions involving the progression of metastatic lung cancer." (PMID 26919096, 2016). "Similar to what we observed as regards cathepsin B secretion, HGF and EGF-induced tumor cell invasion and motility were also significantly reduced following treatment with niclosamide." (PMID 26784896, 2016). "Within solid tumors, MSC can produce and secrete several growth factors such as hepatocyte growth factor (HGF), insulin-like growth factor (IGF1), and fibroblast growth factor (FGF), which can directly influence the tumor cell growth." (PMID 27834810, 2016). "HGF together with its receptor MET, triggers oncogenic signaling events which result in the mesenchymal transformation of tumor cells, resulting in attributes which promote tumor spread, including cell-scattering and invasion." (PMID 27058427, 2016). "Akt activity is downstream of HGF/MET and is involved in tumor angiogenesis through increased secretion of vascular endothelial growth factor and by mediating the expressions of nitric oxide and angiopoietins." (PMID 27338367, 2016). "In vivo, HGF and its receptor, the c-MET proto-oncogene product, are thought to be involved in embryogenesis, tissue reorganization, and tumor progression." (PMID 26090722, 2015). "HGF/SF-MET signalling, however, also plays a key role in the onset of metastasis of a large number of human tumours." (PMID 30090230, 2015). "Tyrosine kinase MET is the receptor for hepatocyte growth factor (HGF/SF) and interaction between MET HGF/SF can induce scattering and migration of (tumour) progenitor cells." (PMID 25673052, 2015). "Neutralizing mAbs against human HGF, such as L2G7, AMG102, and SCH900105 potently suppressed the growth of tumor xenografts in mice." (PMID 28536400, 2015). "Addition of HGF induced MET phosphorylation, leading to the activation of AKT and ERK, and tumor proliferation, confirming that HGF acts mainly as a paracrine factor in HNSCC cells." (PMID 26319934, 2015). "Our results show that serglycin influences tumor growth, angiogenesis, tumor vascular functionality and the availability of the pro-angiogenic modulators VEGF and HGF." (PMID 25978773, 2015). "At the end of the experiment, tumor weight in the control, HCT-116 plus CCD-18co, HCT-116 plus CCD-18co with CPT-11, and HCT-116 plus CCD-18co with CPT-11 plus anti-HGF groups were 1.15 ± 0.27 g, 1.88 ± 0.31 g, 0.61 ± 0.20 g and 0.35 ± 0.15 g, respectively." (PMID 26090722, 2015). "In tumor biopsies, MET was found to be overexpressed in selected types of solid tumors, and HGF was widely detected in the intratumoral spaces of solid tumors." (PMID 28536405, 2015). "The commonly measured biomarkers are circulating HGF and MET levels, MET protein expression levels in tumor tissues, and MET gene amplification, copy number, and mutation, as well as markers related to the crosstalk of related pathways." (PMID 28536405, 2015). "Hepatocyte growth factor (HGF), one of the important growth factors in the tumor microenvironment, has an important role in angiogenesis, tumorigenesis and regeneration." (PMID 26099202, 2015). "Addition of HGF or EGF phosphorylated MET or EGFR, respectively, and demonstrated phosphorylation of Akt and ERK1/2 as well as increased tumor cell viability." (PMID 26496080, 2015). "In our previous studies, ROS-dependent activation of MAPK including Jun N-terminal kinase (JNK) and extracellular signal-regulated kinases (ERK), well known to mediate tumor progression, were required for progression of HepG2 induced by TPA and HGF." (PMID 26416447, 2015).
tumor (continued). "The tumor microenvironment of HCC contains a lot of metastatic factors including transforming growth factor β (TGFβ) and hepatocyte growth factor (HGF), which are capable of triggering HCC metastasis." (PMID 26416447, 2015). "Taken together, these studies highlight that HGF and aberrant c-MET signalling have a critical role in mediating the bi-directional crosstalk between HSC and tumour cells during hepatocarcinogenesis." (PMID 26013123, 2015). "Likewise, these HGF-mediated phosphorylation signals were partially diminished by a parallel incubation with 2.5 μM crizotinib and even more reduced in the presence of 1.25 μM foretinib suggesting the c-Met inhibitor foretinib a potent signaling inhibitor in these tumor cells." (PMID 26436697, 2015). "Medulloblastoma cell lines are most sensitive to exogenous HGF (4 out of 5 cell lines), FGF-2 (3 out of 5 cell lines) and EGF (3 out of 5 cell lines) resulting in increased tumor cell growth." (PMID 26496080, 2015). "Therefore ERK2 may be more essential than ERK1 for the tumor progression of HCC triggered by HGF." (PMID 25607934, 2015). "They release growth factors (e.g., SDF-1α, VEGF, HGF, EGF, FGFs, TGF-β, PDGF), pro-tumorigenic inflammatory signals and matrix metalloproteases promoting angiogenesis, tumor cell proliferation and invasiveness." (PMID 25880005, 2015). "Nevertheless, none of these factors showed significant changes from baseline to best tumor response (ANGPTL4, 2.9 to 3.9 ng/mL, p = 0.16; HGF, 0.79 to 0.75 ng/mL, P = 0.60; VEGF-A121, 0.60 to 0.39 ng/mL, P = 0.26)." (PMID 26620439, 2015). "Important tumor related growth factors which are normally expressed in the developing brain binding RTKs include VEGF, EGF, HGF, FGF and PDGF." (PMID 25799134, 2015). "One molecule that has been shown to be involved in resistance to EGFR inhibitors in different tumor types is MET, the receptor tyrosine-kinase for hepatocyte growth factor (HGF)." (PMID 26319934, 2015). "Mechanistically, the transmigration of anti-tumoral Met+ neutrophils was dependent on expression of high levels of hepatocyte growth factor (HGF), the only ligand for MET, by the tumor." (PMID 26438048, 2015). "Loss of serglycin resulted in a lower number of angiogenic islets, an enhanced perfusion of the tumor vasculature and decreased levels of VEGF and HGF, suggesting that the presence of serglycin influences angiogenesis and vascular function." (PMID 25978773, 2015). "We also showed that HOTAIR recruiting and binding to PRC2 epigenetically represses miR34a, which controls the targets C-Met (HGF/C-Met/Snail pathway) and Snail, thus contributing to GC cell-EMT process and accelerating tumor metastasis." (PMID 26136075, 2015). "Initial secretome characterization studies performed on SD-MSCs showed that they secrete tumor supportive factors such as VEGF-A, HGF, IGF-1." (PMID 25669974, 2015). "EGF, HGF and FGF, which are normally expressed in brain (tumor) tissue, showed to be effective rescue inducing growth factors resulting in increased cell survival especially during treatment with dasatinib (complete rescue) or sorafenib (partial rescue)." (PMID 25799134, 2015). "As a positive control to demonstrate that tumor cells were viable and responsive, they were stimulated with a cocktail of known tumor growth factors consisting of EGF, HGF, and IGF-1." (PMID 25807104, 2015). "Evidence indicate that the two signaling pathways, integrin/ECM and HGF/c-MET, cooperate synergistically to induce FAK activation in an adhesion-dependent manner, leading to enhanced cell adhesion and motility of tumor cells." (PMID 28536400, 2015). "Although its function downstream of HGF has been suggested, our findings are the first to demonstrate the involvement of MAP4K4 downstream of c-Met in tumor cells." (PMID 25625039, 2015).
tumor (continued). "Macrophages and neutrophils are important as providers of pro-angiogenic mediators to the tumor environment, as both cell types are known to express both VEGF and HGF and are present in tumor tissue in large numbers." (PMID 25978773, 2015). "Within the tumor microenvironment, the primary tumor may interact with stromal and inflammatory cells, leading to the secretion of numerous growth factors and cytokines, including hepatocyte growth factor (HGF), epidermal growth factor (EGF), and transforming growth factor-β." (PMID 25607934, 2015). "CAFs can produce tumor-promoting molecules such as TGF-β, FGF, hepatocyte growth factor (HGF), and EGF." (PMID 24966464, 2014). "HGF is one of the factors produced by the MSC and its beneficial effects include mitogens, morphogens, and anti-tumor activities." (PMID 25426285, 2014). "To gain further knowledge of the effects of HGF/SF and Ras inhibition by FTS on tumor cell metabolism, we measured glucose uptake and ATP synthesis in cultured DA3 cells." (PMID 25593982, 2014). "The same biological responses that are strictly regulated by HGF in MET-expressing cells in normal or repairing physiological settings can be subverted and become responsible for tumor development and metastasis." (PMID 28548076, 2014). "These factors such as matrix metalloproteinases (MMPs), hepatocyte growth factor (HGF), and vascular endothelial growth factor (VEGF), play roles in enhancing tumor growth, promoting angiogenesis and generating treatment resistance." (PMID 25050785, 2014). "We sought to evaluate circulating HGF levels in SCLC patients and assess correlation with outcome and EMT features in the tumor." (PMID 25026301, 2014). "Hepatocyte growth factor (HGF) was discovered as a neuronal survival factor but also induces proliferation, migration, and tumor angiogenesis." (PMID 24743777, 2014). "It is possible that the release of EGF and many other RTK ligands (e.g., VEGF, bFGF, HGF) is induced as a consequence of TNFα activation, leading to RTK activation and then to cooperation in the release of CXCL8 by the tumor cells." (PMID 24598028, 2014). "Demonstration of co-expression of SF/HGF and c-MET by immunohistochemistry in the same tumor population seems to support that a subset of SCLC gains cell proliferation through an autocrine stimulatory mechanism." (PMID 25314153, 2014). "Peripheral edema has been associated with treatment with all monoclonal antibodies targeting HGF or MET in combination with various cytotoxic and targeted therapies across multiple tumor types." (PMID 24930887, 2014). "In our study, we selected two alternative mask pairs: tumor (cytokeratin) and macrophage (CD68+) for the HGF analysis and tumor (cytokeratin) and stroma (vimentin+) for the c-Met analysis." (PMID 24952592, 2014). "In summary, induction of HGF synthesis via RNA transferred by MVs activating AKT and ERK1/2 signaling is one of crucial contributors to the pro-tumor effect." (PMID 24797571, 2014). "Hepatocyte growth factor (HGF) and its receptor Met play a significant role in tumour progression partly through upregulation of Src, Stat3 activity, and VEGF expression." (PMID 25231728, 2014). "The HGF/MET signaling axis appears to play an important role in the development and malignant progression of gastroesophageal cancers, particularly in tumor invasiveness and metastasis." (PMID 24930887, 2014). "c-Met, the receptor for hepatocyte growth factor, triggers epithelial-mesenchymal transition (EMT) of cultured cells, which is thought to drive migration of tumor cells and confer on them critical stem cell properties." (PMID 28548077, 2014).
tumor (continued). "SW780 xenograft growth in SCID and human HGF knock-in SCID (hHGF/SCID) mice treated with cabozantinib or vehicle, as well as tumor levels of Met and pMet, were also determined." (PMID 25534569, 2014). "Hepatocyte growth factor (HGF) and its receptor tyrosine kinase c-Met mediate cell motility, migration, increased tumor local invasion, and metastasis." (PMID 24478054, 2014). "In turn, activated fibroblasts secrete HGF, CCL7, UPAR, VEGF, and other factors that promote stemness, growth, survival, and invasiveness of tumor cells." (PMID 24818101, 2014). "MET encodes a receptor tyrosine kinase whose activation by the ligand hepatocyte growth factor results in signaling via the RAS/RAF/MAPK and PI3K pathways to promote tumor proliferation and survival." (PMID 25126591, 2014). "Finally, HGF stimulation of tumor cells may significantly affect the tumor microenvironment." (PMID 28548071, 2014). "Based on the effect of tumor inhibition obtained from the MTT assay, expression of the growth factors EGF, HGF, and VEGF related to tumor growth through real-time quantitative PCR, Western blotting, and ELISA was decreased." (PMID 25068796, 2014). "HGF activation of tumour cell c-met induces gelatinase B/MMP-9 expression, increasing tumor cell motility and scattering." (PMID 24473089, 2014). "Hypoxic conditions in tumor cores are also conducive to the induction of EMT via upregulation of HIF-1α (hypoxia-inducible factor-1α), HGF/SF (hepatocyte growth factor/scatter factor), and other known pro-EMT factors." (PMID 25101115, 2014). "Tumor angiogenesis is regulated by a balance of stimulators (e.g., VEGF-A, hepatocyte growth factor, and FGF-2) and inhibitors (e.g., endostatin and vasohibin)." (PMID 25437864, 2014). "Myofibroblasts secrete high levels of growth factors, such as hepatocyte growth factor (HGF) and vascular endothelial growth factor (VEGF), which can bind to cognate receptors on tumor epithelial cells stimulating proliferation, migration, and invasion." (PMID 25272043, 2014). "Despite being tightly regulated, HGF/MET signaling contributes to oncogenesis and tumor progression in numerous cancers." (PMID 24378750, 2013). "By upregulating hypoxia-inducible factor, hypoxia results in increased HGF expression in tumor and surrounding normal interstitial cells and increased MET expression in tumor and endothelial cells." (PMID 23606971, 2013). "Several evidences show that SULFs are negative regulators of tumor cell growth, and that overexpression of SULFs in tumor cells inhibits cell growth by deregulating several factors, including FGF-2, HB-EGF and HGF." (PMID 24124496, 2013). "Under such a hypoxic state, tumor cells acquire MET via HIF1-dependent cascades, while local HGF protects these cells from hypoxia-induced apoptosis." (PMID 23296269, 2013). "Hepatocyte growth factor (HGF) is a key player during the proliferation phase of liver regeneration and synergistically acts in tumor progression." (PMID 23385555, 2013). "Using NK4 as an HGF-antagonist in experimental cancer models, we demonstrated that endogenous HGF–MET cascade plays a central role in tumor metastasis." (PMID 23296269, 2013). "Among different intracellular signalling transduction pathways, the hepatocyte growth factor (HGF) HGF/MET system is a key driver of oncogenesis and tumor progression in several human malignancies." (PMID 24260160, 2013). "In contrast to anti-HGF antibody, NK4 inhibits not only invasive growth, but also tumor angiogenesis (as a perlecan-binder)." (PMID 23296269, 2013). "It was shown that this effect is related to antiangiogenic influence of thalidomide on different tumor-related mediators: VEGF, basic fibroblast growth factor, hepatocyte growth factor, and IL-8." (PMID 23935247, 2013). "The discovery of NK4 prompted researchers to search HGF-antagonists and MET-inhibitors as anti-tumor drugs." (PMID 23296269, 2013).